C9orf72 (C9orf72-SMCR8 complex subunit)
Diseases named in the same sentence as C9orf72 in open-access papers (continued):
Sharing a sentence is not in itself a finding about the gene and the disease.
frontotemporal dementia (continued). "The most frequent genetic cause of frontotemporal lobar degeneration (FTLD) and amyotrophic lateral sclerosis (ALS) is the expansion of a GGGGCC hexanucleotide repeat in a non-coding region of the chromosome 9 open reading frame 72 (C9orf72) locus." (PMID 28088213, 2017). "Advances in large-scale genetics and genomics have revealed intronic hexanucleotide repeat expansions in the gene encoding C9ORF72 as a main genetic cause of ALS and frontotemporal dementia (FTD), the second most common cause of early-onset dementia after Alzheimer's disease." (PMID 28824365, 2017). "Finally, the investigation of phenotypes associated with the repeat expension r(GGGGCC)exp in C9orf72 that leads to frontotemporal dementia (FTD) and ALS resulted in the detection of cytoplasmic poly(GP) as well as poly(PR) inclusions in iNs but not in fibroblasts." (PMID 29033781, 2017). "Building on recent genetic discoveries, Julie Snowden (University of Manchester, UK) showed the relationship between the diverse clinical characteristics and the underlying pathologies of frontotemporal dementia (FTD) (tau, TDP-43 and FUS) and associated genetic mutations (MAPT, C9orf72 and GRN)." (PMID 27391874, 2015). "An intronic G4C2 hexanucleotide repeat expansion in the first intron or alternative promoter of the uncharacterized C9ORF72 gene was identified as the cause of amyotrophic lateral sclerosis (ALS), frontotemporal lobar degeneration (FTLD), and ALS-FTLD syndrome linked to chromosome 9p21." (PMID 24559645, 2014). "More widespread grey matter changes have been most prominent in studies of the 10–15% of patients with ALS with frank frontotemporal dementia, or in ALS genotypes such as C9orf72, which are more consistently associated with marked frontotemporal dementia-spectrum cognitive impairments." (PMID 24951638, 2014). "ALS and frontotemporal dementia (FTD) are clinically distinct disorders that have recently been brought together with the identification of C9orf72 expansions and the important neuropathological overlap of cytoplasmic inclusions of TAR DNA binding protein 43 (TDP-43) in both disorders." (PMID 23498975, 2013). "The C9orf72 hexanucleotide repeat expansion (G4C2) is the most common genetic cause of amyotrophic lateral sclerosis (ALS) and frontotemporal dementia (FTD), yet targeted therapies remain unavailable." (PMID 41623487, 2026). "The GGGGCC repeat expansion in the chromosome 9 open reading frame 72 gene (C9orf72) is a leading genetic cause of amyotrophic lateral sclerosis and frontotemporal dementia (ALS-FTD)." (PMID 41216506, 2026). "Hexanucleotide repeat expansions (GGGGCC) in the C9orf72 gene represent the most prevalent genetic cause of amyotrophic lateral sclerosis (ALS) and frontotemporal dementia (FTD)." (PMID 41005474, 2025). "The G4C2 repeat expansion in C9orf72 is the most common genetic cause of amyotrophic lateral sclerosis (ALS) and frontotemporal dementia (FTD)." (PMID 41341655, 2025). "The most common genetic cause of amyotrophic lateral sclerosis (ALS) and frontotemporal dementia (FTD) is a hexanucleotide (GGGGCC) repeat expansion in the first intron of C9orf72." (PMID 39945358, 2025). "The expanded GGGGCC hexanucleotide repeat (HRE) in the C9orf72 gene is the most common genetic cause of familial ALS and frontotemporal dementia (FTD)." (PMID 40234983, 2025). "The most recurrent familial cause of amyotrophic lateral sclerosis (ALS) and frontotemporal dementia (FTD) is the presence of an abnormal number of intronic GGGGCC (G4C2) repetitions in the C9orf72 gene, which has been proposed to drive ALS/FTD pathogenesis." (PMID 39670345, 2025). "The C9orf72 HRE is the most common genetic cause of ALS and frontotemporal dementia (FTD) and is uniquely associated with rapid clinical disease progression, onset of symptoms at a young age, and a shorter life span." (PMID 40869392, 2025).
frontotemporal dementia (continued). "Hexanucleotide repeat expansion (HRE) in the non-coding region of the gene C9orf72 is the most prevalent mutation in amyotrophic lateral sclerosis (ALS) and frontotemporal dementia (FTD)." (PMID 40776416, 2025). "A significant proportion of familial amyotrophic lateral sclerosis (ALS) and frontotemporal dementia (FTD) cases exhibit a substantial copy number expansion of the hexanucleotide GGGGCC/GGCCCC sequence in the C9ORF72 gene." (PMID 41394713, 2025). "The C9orf72 hexanucleotide repeat expansion (HRE) is the most common monogenetic cause of amyotrophic lateral sclerosis (ALS) and frontotemporal dementia (FTD)." (PMID 40682810, 2025). "Background and objectives: Frontotemporal dementia (FTD) is a heterogeneous neurodegenerative disorder with autosomal dominant forms most often linked to MAPT, GRN, and C9orf72." (PMID 41149783, 2025). "An intronic hexanucleotide repeat expansion (HRE) in C9orf72 is the commonest monogenetic cause of the neurodegenerative diseases amyotrophic lateral sclerosis (ALS) and frontotemporal dementia (FTD), two clinically and pathologically overlapping syndromes." (PMID 39548852, 2025). "A G4C2 hexanucleotide repeat expansion in C9orf72 is the most common cause of amyotrophic lateral sclerosis and frontotemporal dementia (C9ALS/FTD)." (PMID 39638345, 2025). "Repeat expansions in C9orf72 and mutations in TBK1 have established associations with both ALS and frontotemporal dementia (FTD)." (PMID 40202986, 2025). "The C9orf72 expansion, causing ALS, frontotemporal dementia (FTD) or ALS-FTD phenotypes, is the most common mutation in familial (40%) and sporadic (5–10%) ALS." (PMID 39841674, 2025). "Heterozygous expansion of a GGGGCC repeat in the first intron of the C9orf72 gene is the most frequent known genetic cause of both frontotemporal dementia (FTD) and amyotrophic lateral sclerosis (ALS) (1, –3) (C9-FTD/ALS)." (PMID 38621131, 2024). "Expansion of a G4C2 repeat in the C9orf72 gene is associated with familial Amyotrophic Lateral Sclerosis (ALS) and Frontotemporal Dementia (FTD)." (PMID 38597682, 2024). "C9orf72 hexanucleotide repeat GGGGCC expansion is the most frequent genetic cause of ALS and also the related disease frontotemporal dementia (FTD)." (PMID 39288267, 2024). "C9orf72 hexanucleotide repeat expansions are the most common genetic cause of amyotrophic lateral sclerosis (ALS) and frontotemporal dementia (FTD) in European populations." (PMID 39315390, 2024). "One of the most common genetic causes for both ALS and frontotemporal dementia (FTD), a closely related neurodegenerative condition that shares both genetic and pathological signs with ALS, is a GGGGCC hexanucleotide repeat expansion (HRE) in the C9ORF72 gene (C9-ALS)." (PMID 38664831, 2024). "The GGGGCC hexanucleotide repeat expansion (HRE) in the first intron of C9orf72 (MIM: 614260) is the most common genetic cause of amyotrophic lateral sclerosis (ALS) and frontotemporal dementia (FTD) (FTDALS1 [MIM: 105550]) in populations of European descent." (PMID 38242117, 2024). "Hexanucleotide repeat expansions within the gene C9ORF72 are the most common cause of the neurodegenerative diseases amyotrophic lateral sclerosis (ALS) and frontotemporal dementia (FTD)." (PMID 38658168, 2024). "The pathogenic expansion of the intronic GGGGCC hexanucleotide located in the non-coding region of the C9orf72 gene represents the most frequent genetic cause of amyotrophic lateral sclerosis (ALS) and frontotemporal dementia (FTD)." (PMID 39120329, 2024). "The overlap between Amyotrophic Lateral Sclerosis (ALS) and Frontotemporal Dementia (FTD) represents a significant genetic convergence point of clinical and pathological relevance.A prevalent genetic etiology for both ALS and FTD is the pathogenic amplification of STRs within the C9orf72 intron." (PMID 39039334, 2024).
frontotemporal dementia (continued). "The reduction in POM121 was believed to result from expanded C9orf72 amyotrophic lateral sclerosis overlapping with frontotemporal dementia (ALS/FTD) repeat RNA alone." (PMID 39080077, 2024). "A hexanucleotide GGGGCC repeat expansion in the non-coding region of the C9orf72 gene is the most common genetic mutation identified in patients with amyotrophic lateral sclerosis (ALS) and frontotemporal dementia (FTD)." (PMID 39288267, 2024). "Abnormal expansions of GGGGCC repeat sequence in the noncoding region of the C9orf72 gene is the most common cause of familial amyotrophic lateral sclerosis and frontotemporal dementia (C9-ALS/FTD)." (PMID 37461319, 2023). "C9orf72 hexanucleotide repeat expansion is a common cause of amyotrophic lateral sclerosis (ALS) and frontotemporal dementia (FTD)." (PMID 36936421, 2023). "The expansion of a GGGGCC (G4C2) repeat in the first intron of the C9orf72 gene is the most common genetic cause of amyotrophic lateral sclerosis (ALS) and frontotemporal dementia (FTD)." (PMID 37566088, 2023). "C9orf72 is caused by an intronic GGGGCC repeat and can lead to a frontotemporal dementia (FTD) and amyotrophic lateral sclerosis (ALS)." (PMID 37861103, 2023). "C9orf72 was first described in 2011 following studies in familiar frontotemporal dementia (FTD) and amyotrophic lateral sclerosis (ALS) cases that described a pathogenic GGGGCC hexanucleotide repeat expansion (HRE) in the first intron of the gene." (PMID 37627588, 2023). "RAN translation has been observed on repeats associated with ten disorders: SCA8, DM1, DM2, HD, FXTAS, C9orf72 amyotrophic lateral sclerosis and frontotemporal dementia (C9 ALS/FTD), FXPOI, SCA31, and Fuchs endothelial corneal dystrophy (FECD)." (PMID 37759552, 2023). "An expanded GGGGCC (G4C2) hexanucleotide repeat in C9orf72 is the most common genetic cause of ALS and frontotemporal dementia (FTD); therefore, the resulting disease is known as C9ALS/FTD." (PMID 37681895, 2023). "The most frequent known causes of amyotrophic lateral sclerosis (ALS) and frontotemporal dementia (FTD) are mutations in the C9orf72 gene, which account for 40% of familial and 5% of sporadic ALS cases, and act as a main genetic cause of FTD." (PMID 37138766, 2023). "Hexanucleotide repeat expansions in C9orf72 are the most common cause of familial amyotrophic lateral sclerosis (ALS) and frontotemporal dementia (FTD)." (PMID 35026048, 2022). "A common genetic factor in patients with ALS and frontotemporal dementia (FTD) is the extension of the GGGGCC repeat within intron 1 of Chromosome 9 open reading frame 72 (C9orf72) gene." (PMID 35765969, 2022). "In neurons or brain organoids derived from patients carrying the C9orf72 repeat expansion associated with amyotrophic lateral sclerosis (ALS) and frontotemporal dementia (FTD), the eSG formation was enhanced, and the clearance of conventional SGs was impaired." (PMID 36151083, 2022). "A hexanucleotide GGGGCC (G4C2) repeat expansion in the C9orf72 gene is the most common cause of amyotrophic lateral sclerosis (ALS) and frontotemporal dementia (FTD)." (PMID 36619668, 2022). "Toxic dipeptide-repeat (DPR) proteins are produced from expanded G4C2 repeats in the C9ORF72 gene, the most common genetic cause of amyotrophic lateral sclerosis (ALS) and frontotemporal dementia (FTD)." (PMID 35589706, 2022). "An intronic hexanucleotide repeat expansion (G4C2) in the C9orf72 gene is the most common genetic cause of amyotrophic lateral sclerosis (ALS) and frontotemporal dementia (FTD) (referred to as C9ALS/FTD)." (PMID 35740026, 2022). "One of the most well-studied examples is the expansion of the hexanucleotide GGGGGC in the first intron of the C9orf72 gene which results in frontotemporal dementia (FTD) and amyotrophic lateral sclerosis (ALS)." (PMID 35765654, 2022).
frontotemporal dementia (continued). "The phenotypic variability of overlap syndromes is occasionally explained by the presence of pathogenic mutations in several genes, some recognized as causative genes for sporadic and familial ALS and Frontotemporal Dementia (FTD) such as C9orf72." (PMID 35832068, 2022). "A hexanucleotide repeat expansion in the C9orf72 gene is the most common genetic cause of amyotrophic lateral sclerosis (ALS) and frontotemporal dementia (FTD) with synaptic dysfunction identified as an early pathological hallmark." (PMID 34491551, 2022). "Abnormally expanded GGGGCC hexanucleotide repeats in the first intron of C9orf72 were reported as the most common genetic cause of familial ALS (FALS) and frontotemporal dementia (FTD)." (PMID 34362180, 2021). "The hexanucleotide repeat expansion, GGGGCC (G4C2), within the first intron of the C9orf72 gene is known to be the most common genetic cause of both amyotrophic lateral sclerosis (ALS) and frontotemporal dementia (FTD)." (PMID 34048588, 2021). "Increased numbers of the G4C2 repeats in the C9orf72 gene have been genetically associated with neurodegeneration in amyotrophic lateral sclerosis (ALS) and frontotemporal dementia (FTD) patients." (PMID 34785657, 2021). "Moreover, some of the genes identified in ALS patients are also causative for other neurodegenerative disorders, such as C9orf72 and TARDBP for frontotemporal dementia (FTD) and Parkinson’s disease, and SPG7 and SPG11 for hereditary spastic paraplegia, indicating shared pathomechanisms." (PMID 35052424, 2021). "In biological systems, for example, aberrant amplification of the hexanucleotide GGGGCC (G4C2) repeated in the human C9ORF72 gene is the most common genetic factor found behind frontotemporal dementia (FTD) and amyotrophic lateral sclerosis (ALS)." (PMID 34277575, 2021). "The expanded GGGGCC repeat mutation in the C9orf72 gene is the most common genetic cause of the neurodegenerative diseases amyotrophic lateral sclerosis (ALS) and frontotemporal dementia (FTD)." (PMID 33495278, 2021). "Expansion of a GGGGCC hexanucleotide repeat (hereafter G4C2) within the first intron of the C9orf72 gene is the most frequent genetic cause of amyotrophic lateral sclerosis (ALS) and frontotemporal dementia (FTD)." (PMID 34161229, 2021). "Furthermore, via its interaction with the chromosome 9 open reading frame 72 (C9orf72) gene product, implicated in amyotrophic lateral sclerosis (ALS) and frontotemporal dementia (FTD), additional roles for RAB39B in postsynaptic GluR subunit expression and autophagy have also been established." (PMID 32762091, 2021). "A GGGGCC hexanucleotide repeat expansion in the C9orf72 gene is the most common genetic cause of amyotrophic lateral sclerosis and frontotemporal dementia (C9ALS/FTD) and is also associated with sporadic forms." (PMID 34769517, 2021). "Since the discovery of the C9orf72 repeat expansion mutation as causative for chromosome 9-linked amyotrophic lateral sclerosis (ALS) and frontotemporal dementia (FTD) in 2011, a multitude of cellular pathways have been implicated." (PMID 33967699, 2021). "Similar to other neurodegenerative diseases, frontotemporal dementia (FTD) may have familial forms, which are associated with mutations in the genes coding for progranulin (GRN), chromosome 9 open reading frame 72 (C9orf72), or microtubule-associated protein tau (MAPT)." (PMID 34108859, 2021). "A hexanucleotide repeat expansion GGGGCC in the non-coding region of C9orf72 is the most common cause of inherited amyotrophic lateral sclerosis (ALS) and frontotemporal dementia (FTD)." (PMID 34654821, 2021). "A large G4C2-repeat expansion in C9orf72 is the most common genetic cause of amyotrophic lateral sclerosis (ALS) and frontotemporal dementia (FTD)." (PMID 33558503, 2021). "A hexanucleotide repeat expansion in the C9orf72 gene is the most common genetic cause of amyotrophic lateral sclerosis (ALS) and frontotemporal dementia (FTD)." (PMID 33837088, 2021).
frontotemporal dementia (continued). "Aberrant hexanucleotide repeat expansions in C9orf72 are the most common genetic change underlying amyotrophic lateral sclerosis (ALS) and frontotemporal dementia (FTD)." (PMID 33578948, 2021). "We report in vivo patterns of neuroinflammation and abnormal protein aggregation in seven cases of familial frontotemporal dementia (FTD) with mutations in MAPT, GRN and C9orf72 genes." (PMID 33122395, 2021). "An expansion of repeated nucleotides in the non-coding region of the C9orf72 gene has been linked to the neurodegenerative diseases amyotrophic lateral sclerosis (ALS) and frontotemporal dementia (FTD)." (PMID 32282804, 2020). "Expansion of a hexanucleotide repeat (GGGGCC) in the C9orf72 gene was shown to be the major cause of familial amyotrophic lateral sclerosis (ALS) and frontotemporal dementia (FTD)." (PMID 33633744, 2020). "In a study of frontotemporal dementia (FTD), symptomatic FTD patients with GRN mutation had more WMH load than patients with microtubule-associated protein tau (MAPT) and chromosome 9 open reading frame 72 (C9orf72) gene mutations." (PMID 33352859, 2020). "The hexanucleotide (G4C2) repeat expansion in C9orf72 is the most common genetic cause of ALS and is also common in frontotemporal dementia (FTD)." (PMID 32471232, 2020). "The C9orf72 hexanucleotide repeat expansion is the most common genetic cause of amyotrophic lateral sclerosis (ALS) and frontotemporal dementia (FTD) in populations of European descent." (PMID 33168078, 2020). "The most common cause of amyotrophic lateral sclerosis (ALS) and frontotemporal dementia (FTD) is an intronic hexanucleotide repeat expansion in the C9orf72 gene." (PMID 32347002, 2020). "We sought to characterize C9orf72 expansions in relation to genetic ancestry and age at onset (AAO) and to use these measures to discriminate the behavioral from the language variant syndrome in a large pan-European cohort of frontotemporal lobar degeneration (FTLD) cases." (PMID 32943482, 2020). "Expansion of the (GGGGCC)n repeats in the C9orf72 gene is associated with the neurological disorders amyotrophic lateral sclerosis (ALS) and frontotemporal dementia (FTD)." (PMID 32059547, 2020). "A different expansion of G4C2 repeats in the c9orf72 gene is the most causative factor of amyotrophic lateral sclerosis (ALS) and frontotemporal dementia (FTD)." (PMID 32340368, 2020). "A hexanucleotide repeat expansion (HRE) mutation in a non-coding region of the C9orf72 gene is currently the most common known cause of amyotrophic lateral sclerosis (ALS) and frontotemporal dementia (FTD)." (PMID 31835664, 2019). "Here we analyzed whether different cellular stressors promote RAN translation of dipeptide repeats (DPRs) associated with the G4C2 hexanucleotide expansions in C9orf72, the most common genetic cause of amyotrophic lateral sclerosis (ALS) and frontotemporal dementia (FTD)." (PMID 30617154, 2019). "A repeat expansion mutation in the C9orf72 gene is the most common known genetic cause of amyotrophic lateral sclerosis (ALS) and frontotemporal dementia (FTD)." (PMID 31835664, 2019). "Hexanucleotide (G4C2) repeat expansions within the first intron of C9orf72 are the most common known genetic cause of both ALS and frontotemporal dementia (FTD)." (PMID 31651360, 2019). "In this report, we describe [18F]AV‐1451 binding in a patient with a clear familial case of frontotemporal dementia (FTD) due to a hexanucleotide repeat expansion in the C9orf72 gene." (PMID 30349864, 2018). "TDP-43 inclusions also characterize patients with GGGGCC (G4C2) hexanucleotide repeat expansion in C9orf72 that causes the most common genetic form of amyotrophic lateral sclerosis and frontotemporal dementia (C9ALS/FTD)." (PMID 30239641, 2018).